CBX2 (chromobox 2)
Diseases named in the same sentence as CBX2 in open-access papers (continued):
Sharing a sentence is not in itself a finding about the gene and the disease.
ovarian carcinoma (15 papers, 2018 to 2026). A malignant neoplasm originating from the surface ovarian epithelium. "Loss of CBX2 expression can sensitize ovarian cancer to chemotherapy." (PMID 39793896, 2025). "For instance, USP33 deubiquitinates and stabilizes HIF-2α, promoting the hypoxia response in glioma stem cells, and its elevated expression accelerates ovarian cancer progression by stabilizing CBX2." (PMID 40695806, 2025). "A recent study reported that one CBX2 inhibitory peptide can inhibit ovarian cancer cell proliferation and tumor progression in vivo." (PMID 39793896, 2025). "In ovarian cancer, miR-136 enhances paclitaxel sensitivity and inhibits tumor progression by targeting CBX2." (PMID 36869031, 2023). "To summarize, circ_0061140 sponged miR-136 and elevated the expression of CBX2 in ovarian cancer, leading to PTX resistance and tumor malignant progression." (PMID 38152652, 2023). "CBX2 was identified as being overexpressed in ovarian cancer, BC, CRC and osteosarcoma, and high CBX2 levels predicted unfavorable outcomes in ovarian cancer and BC." (PMID 36140750, 2022). "Subsequently, qRT-PCR results showed that CBX2 mRNA expression was dramatically upregulated in PTX-resistant ovarian cancer tissues and PTX-resistant SKOV3 and HeyA8 cells as compared to control groups." (PMID 34649611, 2021). "Western blot data also displayed the protein expression of CBX2 was obviously increased in PTX-resistant ovarian cancer tissues and SKOV3/PTX and HeyA8/PTX cells as compared to control groups." (PMID 34649611, 2021). "Compared with the limited data on the role of CBX4 in ovarian cancer, CBX2 was employed as the potential target gene of miR-136." (PMID 34649611, 2021). "Circ_0061140 absence hindered cell proliferation, migration and invasion, and improved PTX sensitivity and accelerated cell apoptosis via downregulating CBX2 expression through binding to miR-136 in PTX-resistant ovarian cancer in vitro." (PMID 34649611, 2021). "Circ_0061140 silencing repressed the progression and PTX resistance of ovarian cancer by downregulating CBX2 expression via sponging miR-136, which provided novel insight into studying the therapy of ovarian cancer with PTX." (PMID 34649611, 2021). "MiR‐342 has been reported to target CBX2 and inhibit cell proliferation, metastasis and invasion of ovarian cancer cells." (PMID 33089952, 2020). "In addition, the knockdown of CBX2 reduced anchorage-independent proliferation and enhanced anoikis-dependent apoptosis in ovarian cancer." (PMID 36140750, 2022). "However, upregulated CBX2 expression was significantly associated with a positive PFS in women with clinical stages III and IV ovarian cancer." (PMID 32742466, 2020). "Furthermore, chromobox 2 (CBX2) was found to be a target of miR-136 in ovarian cancer." (PMID 38152652, 2023). "Thus, we hypothesized that circ_0061140 regulated PTX sensitivity in ovarian cancer by miR-136/CBX2 pathway." (PMID 34649611, 2021). "Meanwhile, these data also showed that miR-136 regulated the sensitivity of ovarian cancer to PTX and tumor progression by targeting CBX2." (PMID 34649611, 2021). "Further, the regulatory relationship of miR-136 and CBX2 in the progression and PTX sensitivity of ovarian cancer was explored." (PMID 34649611, 2021). "Conversely, CBX2 expression at the transcriptional level was significantly related to unfavorable OS in stage III and IV ovarian cancer patients." (PMID 32742466, 2020). "Recent studies have confirmed that CBX2 acts as an oncogene in several cancers, including BRCA, HCC, PRCA, and ovarian cancer (OVCA)." (PMID 33344640, 2020). "Subsequently, IHC analysis found that CBX1, CBX2 and CBX3 expression was significantly higher in ovarian cancer tissues than in the corresponding controls." (PMID 32742466, 2020). "Specifically, high expression levels of CBX1, CBX2 and CBX3 all predicted unfavorable OS and PFS in all ovarian cancer patients." (PMID 32742466, 2020).
ovarian carcinoma (continued). "Therefore, CBX2 might be a potential unfavorable prognostic candidate for ovarian cancer." (PMID 32742466, 2020). "Elevated expression of CBX2 mRNA did not have any influence on prognosis in stage I and II ovarian cancer patients." (PMID 32742466, 2020). "In other ovarian cancer histosubtypes, we noted a lack of CBX2 expression suggesting the oncogenic effects of CBX2 are HGSOC specific." (PMID 30478317, 2018). "Functional experiments also displayed that CBX2 overexpression restored the effects of miR-136 mimic on tumor progression and PTX sensitivity, which demonstrated that CBX2 acted as an oncogene and could inhibit PTX sensitivity in PTX-resistant ovarian cancer." (PMID 34649611, 2021). "In addition, a further novel finding was that despite the mRNA expression levels of CBX2/4/5 were not statistically different between OV tissues and normal tissues, their mRNA expression levels in ovarian cancer tissues were significantly correlated with individual cancer stages." (PMID 35155439, 2022). "For CBX2, an increased level of CBX2 mRNA was not involved in OS or PFS for all grades of ovarian cancer patients." (PMID 32742466, 2020).
hepatocellular carcinoma (13 papers, 2019 to 2025). A malignant tumor that arises from hepatocytes. "Previous studies have shown that high expression of CBX2 is associated with worse survival in hepatocellular carcinoma, high-grade serous ovarian cancer, and lung adenocarcinoma." (PMID 37489460, 2023). "In hepatoma, an obvious high expression of CBX2 is regarded as an independent poor prognostic factor, and down-regulation of CBX2 expression inhibits the development of liver cancer." (PMID 38702698, 2024). "A previous report confirmed that CBX2 knockdown can significantly suppress the proliferation and enhance apoptosis of hepatocellular carcinoma (HCC) cells in vivo and in vitro." (PMID 38495501, 2024). "Results indicated that high expression of CBX2 and CBX3 proteins was significantly associated with poor prognosis for hepatocellular carcinoma patients." (PMID 35677563, 2022). "Results revealed that high expression of CBX1, CBX2, CBX3, CBX6, and CBX8 was associated with poor survival rates of hepatocellular carcinoma patients." (PMID 35677563, 2022). "In hepatocellular carcinoma (HCC), CBX2 was found to promote HCC cells proliferation by decreasing YAP phosphorylation." (PMID 35155439, 2022). "In hepatocellular carcinoma, the knockdown of CBX2 restrained the proliferation of HCC cells and increased the phosphorylation of YAP." (PMID 34046352, 2021). "In hepatocellular carcinoma (HCC) cells, CBX2 downregulation slows proliferation and induces apoptosis." (PMID 40175347, 2025). "The ceRNA regulatory network involving CBX2, PBK, and AP002478.1 influences the progression of hepatocellular carcinoma." (PMID 38355480, 2024). "Higher expression of CBX7 was correlated with better prognosis in hepatocellular carcinoma, whereas CBX1, CBX2, CBX3, CBX6 and CBX8 were identified as independent prognostic factors for poor overall survival." (PMID 35637952, 2022). "A previous study reported that the increased mRNA expression of HP1-β/γ (CBX1/3) and CBX2/6/8 was correlated with a worse OS, while the overexpression of CBX7 was related to a greater OS in patients with hepatocellular carcinoma." (PMID 34046352, 2021). "Recent studies have suggested that CBX2 and CBX6 act as oncogenes in hepatocellular carcinoma (HCC)." (PMID 34321009, 2021).
gastric cancer (9 papers, 2021 to 2025). A primary or metastatic malignant neoplasm involving the stomach. "In gastric cancer (GC) cell lines, high CBX2 expression promotes proliferation, invasion, and migration by activating the YAP/β-catenin pathway." (PMID 40175347, 2025). "The mRNA and protein expression levels of CBX2/3 in gastric cancer tissues were significantly higher than in normal tissues, whereas CBX6/7 were down-regulated in gastric cancer." (PMID 35969177, 2022). "The present study demonstrated that CBX2 production was also upregulated in gastric cancer tissues compared with normal tissues." (PMID 34117289, 2021). "Expression levels of mRNA and protein of CBX2/3 were greatly increased in gastric cancer patients." (PMID 37168445, 2023). "Protein levels of CBX2/3 increased in gastric cancer tissues." (PMID 35969177, 2022). "CBX2 had been proved to be highly expressed in Gastric cancer (GC) cells." (PMID 36982591, 2023). "A prognostic gene model based on five CBX genes (CBX1, CBX2, CBX3, CBX7, and CBX8) predicted the overall survival of gastric cancer patients." (PMID 35969177, 2022). "The transcription levels of CBX2, CBX3, CBX4 and CBX5 were significantly enhanced, whereas the mRNA level of CBX7 was decreased in gastric cancer tissues compared with normal tissues." (PMID 34117289, 2021). "Again, CBX2 has been found to regulate proliferation and apoptosis by phosphorylating YAS in hepatocellular cells; it promoted the proliferation, invasion, and migration of gastric cancer by activating the YAP/beta-catenin pathway." (PMID 36292141, 2022). "Moreover, we found a prognostic CBXs model comprising five genes (CBX1, CBX2, CBX3, CBX7, and CBX8) for gastric cancer patients." (PMID 35969177, 2022).
lung adenocarcinoma (8 papers, 2015 to 2024). A carcinoma that arises from the lung and is characterized by the presence of malignant glandular epithelial cells. "The role of CBX2 in other solid cancers should also be investigated, as a similar overexpression profile for CBX2 is observed in endometrial and lung adenocarcinoma." (PMID 30820027, 2019). "The relative mRNA levels of CBX2 and EZH2 were therefore assessed in SCLC and compared to two epithelial lung cancer subtypes, lung adenocarcinoma (AC) and squamous cell carcinoma (SqCC)." (PMID 25859291, 2015). "In addition to BCa, CBX2 expression is elevated in GBM and lung adenocarcinoma compared to normal tissue." (PMID 35884550, 2022).
colorectal cancer (7 papers, 2021 to 2025). A primary or metastatic malignant neoplasm that affects the colon or rectum. "Herein, we found that CBX2 overexpression in colorectal cancer tissue compared with adjacent tissues." (PMID 38495501, 2024). "In this study, we discovered that elevated CBX2 expression was positively related to the malignancy of colorectal cancer, as well as provided new insights into its functional role in promoting CRC proliferation and migration." (PMID 38495501, 2024). "We therefore intend to continue to explore the effects of CBX2 on colorectal cancer in CBX2 knockout mice and transgenic mice." (PMID 38495501, 2024). "Furthermore, studies on colorectal cancer (CRC) showed that the CBX2 gene was significantly upregulated in CRC tissues compared to normal tissues, and this may be associated with poor prognosis." (PMID 37489460, 2023). "Consistently, the downregulation of CBX2 significantly upregulated apoptosis in HCC, HGSOC, acute myeloid leukemia, and colorectal cancer cells." (PMID 37662906, 2023).
glioma (7 papers, 2018 to 2025). A benign or malignant brain and spinal cord tumor that arises from glial cells (astrocytes, oligodendrocytes, ependymal cells). "Given the prevalence of PIK3CA mutations in glioma tumors, we initiated an analysis of the association between CBX2 and PIK3CA mutations using TCGA datasets." (PMID 39114365, 2024). "However, the cellular function and the underlying molecular mechanisms of CBX2 in gliomas are still unknown." (PMID 39114365, 2024). "To further validate the involvement of CBX2 in glioma progression, we introduced exogenous CBX2 into LN229 cells." (PMID 39114365, 2024). "In summary, we found that CBX2 is overexpressed in gliomas and is associated with high tumor grade, TMZ chemoresistance, and poor prognosis in glioma patients." (PMID 39114365, 2024). "We analysed the correlation between the expression level of CBX2 and the clinicopathological features of glioma patients." (PMID 39114365, 2024). "In our study, we observed a substantial upregulation of CBX2 expression in glioma, which displayed a strong correlation with pathological grade, chemoresistance, and unfavorable prognosis." (PMID 39114365, 2024). "Our research unveils a comprehensive understanding of how CBX2 impacts the tumorigenesis, progression, chemoresistance, and prognosis of glioma." (PMID 39114365, 2024). "In this study, we identified that CBX2 was significantly upregulated in glioma through comprehensive analysis of transcriptomic data from the Cancer Genome Atlas (TCGA) and Chinese Glioma Genome Atlas (CGGA) databases." (PMID 39114365, 2024). "Immunohistochemical (IHC) analysis showed that a high expression level of CBX2 predicts a poorer prognosis in glioma patients." (PMID 39114365, 2024). "Conversely, CBX2 knockdown led to a significant inhibition of glioma cell growth and a reduction in chemoresistance." (PMID 39114365, 2024). "When the phosphorylation of AKT was disturbed, the effect of CBX2 on glioma proliferation and chemoresistance was abolished, suggesting that CBX2 promotes glioma progression and chemoresistance through PTEN-controlled AKT activation." (PMID 39114365, 2024). "We used TCGA, GTEx and CGGA datasets to analyse the expression level and clinical significance of CBX2 in glioma." (PMID 39114365, 2024). "Through a series of in vivo and in vitro experiments, we established that heightened CBX2 expression facilitated glioma cell proliferation and bolstered resistance to chemotherapy." (PMID 39114365, 2024). "To substantiate the regulatory connection between CBX2 and PTEN, we assessed alterations in the mRNA and protein expression of PTEN in glioma cells following CBX2 knockdown or overexpression." (PMID 39114365, 2024). "In summary, these data suggest that suppression of CBX2 in glioma cells can inhibit cell viability, reduce cell proliferation and enhance TMZ chemosensitivity." (PMID 39114365, 2024). "Kaplan-Meier survival analysis showed that glioma with higher CBX2 levels had shorter overall survival times and worse prognoses than patients with lower CBX2 levels (p < 0.0001)." (PMID 39114365, 2024). "In the current study, through bioinformatics analysis, we found that CBX2 is upregulated in gliomas and is closely related to pathological grade and a poor prognosis, which was verified by IHC analysis of clinical samples." (PMID 39114365, 2024). "Correlation of the CBX2 expression with clinical and pathological characteristics in tissue samples from glioma patients." (PMID 39114365, 2024). "Both in vivo and in vitro experiments confirmed that overexpression of CBX2 promoted glioma proliferation and chemoresistance." (PMID 39114365, 2024). "Pharmacological targeting CBX2 could provide a novel therapeutic approach for the treatment of gliomas." (PMID 39114365, 2024). "Furthermore, the expression level of CBX2 is correlated with higher glioma pathological stage and shorter overall survival time in glioma patients." (PMID 39114365, 2024).
glioma (continued). "CBX2 promotes glioma cell proliferation and invasion through the PI3K/AKT pathway." (PMID 39114365, 2024). "Furthermore, it presents CBX2 as a promising therapeutic target for drug development and clinical management of glioma." (PMID 39114365, 2024). "In addition, we found that CBX2 is closely related to glioma chemoresistance, and tumorigenesis studies in vivo also strongly support its role in glioma progression and chemoresistance." (PMID 39114365, 2024). "However, knockdown of CBX2 reversed these effects in glioma." (PMID 39114365, 2024). "However, the precise role of CBX2 in glioma has remained elusive." (PMID 39114365, 2024). "CDCA6, also known as CBX2 (chromobox 2), promotes glioma cell proliferation and invasiveness by participating in Akt/PI3K pathway." (PMID 38181024, 2024). "In the current study, the molecular mechanism investigation showed that CBX2 activates the AKT/mTOR signalling pathway by inhibiting the expression of PTEN and affects the carcinogenicity and chemoresistance of glioma cells." (PMID 39114365, 2024). "We also detected the CBX2 level in A172, LN18, LN229 and T98G glioma cell lines using WB, and the results showed that compared with normal glial cells (HEB), CBX2 levels were significantly upregulated in all glioma cell lines, especially in LN18 cells." (PMID 39114365, 2024). "To assess the impact of CBX2 on tumorigenicity and TMZ resistance of glioma cells in vivo, we established a mouse model of intracranial xenograft tumors." (PMID 39114365, 2024). "Examining the potential molecular mechanism, we found that CBX2 inhibits PTEN transcription by recruiting EZH2 to regulate the H3K27me3 level of the PTEN promoter and thus activates the AKT/mTOR pathway to accelerate glioma progression and TMZ chemoresistance." (PMID 39114365, 2024). "In this study, we proved the binding of CBX2 and EZH2 in glioma." (PMID 39114365, 2024). "We performed co-IP experiments and proved the binding of CBX2 and EZH2 in glioma cells." (PMID 39114365, 2024). "Subsequently, we implemented CBX2-knockdown LN229R, and the results demonstrated that CBX2 knockdown not only slowed glioma growth and prolonged survival without TMZ treatment but also significantly enhanced tumor suppression and extended survival when combined with TMZ treatment." (PMID 39114365, 2024).
lung carcinoma (7 papers, 2015 to 2025). "Next, the expression of AC144450.1, miR-424-5p, and CBX2 was individually knocked down in lung cancer cells to examine the regulatory effects of the ceRNA network on cell proliferation and cell cycle." (PMID 38355480, 2024). "Thereafter, we predicted the enrichment of genes co-regulated by two or more genes in the AC144450.1/miR-424-5p/CBX2 axis on the lung cancer malignant progression pathway." (PMID 38355480, 2024). "Previous studies have demonstrated that AC144450.1, miR-424-5p, and CBX2 are potential prognostic biomarkers for lung cancer." (PMID 38355480, 2024). "Altogether, the results revealed that AC144450.1, miR-424-5p, and CBX2 individually regulated the malignant progression of lung cancer." (PMID 38355480, 2024). "Altogether, the prognostic model constructed based on AC144450.1, miR-424-5p, and CBX2 detected lung cancer and predicted the prognosis more accurately." (PMID 38355480, 2024). "Altogether, these results suggest that miR-424-5p acts as a regulator of CBX2 and affects the malignant behavior of lung cancer." (PMID 38355480, 2024). "Altogether, these results indicate that AC144450.1 and miR-424-5p regulate the CBX2 protein in lung cancer, which is consistent with the ceRNA hypothesis." (PMID 38355480, 2024). "However, the precise role of AC144450.1, miR-424-5p, and CBX2 in the malignant progression of lung cancer remains unclear." (PMID 38355480, 2024). "Expression of the cPRC1 protein chromobox 2 (CBX2) is elevated in a number of solid tumours, including colon, prostate, breast, stomach, glioblastoma (GBM), and lung cancer; indicating a potential oncogenic role for this protein." (PMID 35884550, 2022). "In lung cancer, the expression of CBX1, CBX2, CBX3, and CBX5 was up-regulated, while CBX7 was down-regulated." (PMID 34966411, 2021). "Supporting this idea, we observed preferential overexpression of PcG genes CBX2 and EZH2 in SCLC, which represents a lung cancer subtype with neuroendocrine differentiation." (PMID 25859291, 2015).